ALB (albumin)
Diseases named in the same sentence as ALB in open-access papers (continued):
Sharing a sentence is not in itself a finding about the gene and the disease.
acalculous cholecystitis (3 papers, 2021 to 2024). Inflammation of the gallbladder in the absence of gallstones. "Only ALB and TB were closely associated with acalculous cholecystitis in patients with HE after correction using multivariate analysis." (PMID 37095526, 2023). "After correction by multivariate analysis, albumin and total bile acid were found to be closely related to acalculous cholecystitis in HE." (PMID 37095526, 2023). "The univariate regression analysis showed that age and having a TG18 grade III status, acalculous cholecystitis, an albumin level < 28 g/L, CCVD, and a history of malignancy were the factors influencing a patient’s failure to undergo interval cholecystectomy." (PMID 34711183, 2021).
acromegaly (3 papers, 2024 to 2025). Acromegaly is an acquired disorder related to excessive production of growth hormone (GH) and characterized by progressive somatic disfigurement (mainly involving the face and extremities) and systemic manifestations. "Among liver enzymes, AST (p < 0.001) and ALP (p = 0.003) levels were significantly elevated in the acromegaly group, whereas albumin (p < 0.001) and hemoglobin (p = 0.011) levels were higher in the controls." (PMID 40725515, 2025). "Acromegaly patients did not have a higher risk of increased urinary albumin excretion." (PMID 39329880, 2024). "It was noticed that urinary albumin and UACR were higher in patients diagnosed with acromegaly versus the patients in the control group." (PMID 39329880, 2024).
adenoma (3 papers, 2021 to 2024). A neoplasm arising from the epithelium. "In contrast, the ALB+ hepatocyte population differed completely between normal tissues (clusters #9 and #12) and adenomas (cluster #7)." (PMID 38201587, 2023). "Our binary logistic regression analysis investigates the predictors of fracture presence using age, adenoma size, PTH level, albumin-corrected calcemia, and 25(OH)D level as covariables." (PMID 39040613, 2024).
adenopathy (3 papers, 2019 to 2025). "Thus, it is critical for veterinary clinicians to know breed predispositions for IL and understand that significant negative correlations between lymphatic disease and serum albumin have been demonstrated in multiple studies even in cases where inflammation predominates histologically." (PMID 36290177, 2022).
allergic asthma (3 papers, 2005 to 2024). A asthma with a basis in a pathological type I hypersensitivity reaction. "In allergic asthma luminal levels of a large protein such as fibrinogen may better than albumin reflect the plasma exudation process, a hallmark of the disease especially at exacerbations." (PMID 16086832, 2005).
aphthous ulcer (3 papers, 2014 to 2022). "Also, acute phase reactants ESR and CRP levels were significantly higher and albumin and vitamin B12 levels were significantly lower in the aphthous ulcer group (p<0.05)." (PMID 24560378, 2014). "The goal of this study was to investigate whether there is a correlation between C-reactive protein to albumin ratio (CAR) and oral ulcer activity in patients with recurrent aphthous stomatitis." (PMID 31803551, 2019).
Apnea (3 papers, 2019 to 2024). Lack of breathing with no movement of the respiratory muscles and no exchange of air in the lungs. "It has been suggested that low serum albumin levels appear to be associated with an increased risk of apnea and are potentially a predictor of future apnea." (PMID 39026682, 2024). "In unadjusted analyses, apnea was associated with younger age, preterm birth, weight-for-age z score, and low albumin (odds ratio [OR], 12.69; 95% CI, 3.23-49.82)." (PMID 31314114, 2019). "Low serum albumin levels appeared to be associated with increased risk of apnea after adjustment for known apnea risk factors." (PMID 31314114, 2019). "After adjustment for age, preterm birth, and weight-for-age z score, low serum albumin levels remained statistically significantly associated with apnea (OR, 4.42; 95% CI, 1.21-16.18)." (PMID 31314114, 2019). "After adjustment for age, preterm birth, and weight-for-age z score, low serum albumin levels remained associated with a statistically significantly higher risk of apnea (OR, 4.42; 95% CI, 1.21-16.18)." (PMID 31314114, 2019). "In a large, prospective, multicenter cohort of infants hospitalized for bronchiolitis, low serum albumin levels were associated with increased risk of apnea after adjustment for known apnea risk factors (young age, preterm birth, and weight for age at hospitalization)." (PMID 31314114, 2019). "In a large, prospective, multicenter cohort of infants hospitalized for bronchiolitis, low serum albumin level appeared to be associated with increased risk of apnea after adjustment for known apnea risk factors (young age, preterm birth, and weight-for-age z score)." (PMID 31314114, 2019). "Although needing replication and lacking a clear mechanism, these results suggest, for the first time to our knowledge, that albumin levels are a promising line of inquiry to help identify apnea in children hospitalized for bronchiolitis." (PMID 31314114, 2019). "The prevalence of apnea among infants with a normal albumin level was 0.5% compared with a prevalence of 5.7% among all infants with a low albumin level and 14.6% among infants younger than 1 month with low albumin levels." (PMID 31314114, 2019). "Nonetheless, serum albumin levels may eventually play a role in identifying apnea in infants with severe bronchiolitis." (PMID 31314114, 2019). "Albumin levels may have a role in identifying apnea in bronchiolitis." (PMID 31314114, 2019). "Among the 25 infants (2.5%) with apnea while hospitalized, the median (IQR) serum albumin level was 3.5 (3.1-3.6) g/dL, and 22 (88.0%) had low serum albumin levels." (PMID 31314114, 2019). "Twenty-five infants (2.5%) had apnea while hospitalized, composing the cases for the primary analysis; among these 25 infants, the median (IQR) serum albumin level was 3.5 (3.1-3.6) g/dL, and 22 (88.0%) had low serum albumin levels." (PMID 31314114, 2019). "EMPA resulted in a similar placebo-adjusted reduction in the urinary albumin-to-creatinine ratio (UACR) over a mean period of 3.1 years, regardless of Obstructive Sleep Apnea status at baseline." (PMID 36407420, 2022).
artery disease (3 papers, 2021 to 2024). "The C-reactive protein–albumin–lymphocyte (CALLY) indexis a novel inflammatory biomarker, and its association with the prognosis ofcoronary artery disease (CAD) after percutaneous coronary intervention (PCI) hasnot previously been studied." (PMID 39076545, 2024).
artery stenosis (3 papers, 2024 to 2026). "The final multivariate analysis model included baseline creatinine level, baseline serum albumin level, and the presence of renal artery stenosis." (PMID 40686716, 2025). "Analysis revealed that age, weight, BMI, CHA2DS2-VASc score, Killp classification, serum albumin, TG, Scr, eGFR, lymphocyte count, RBC, hemoglobin, Hs-CRP, BNP, PNI, LAD, LVEF, and left circumflex artery stenosis were statistically significant variables." (PMID 38562185, 2024).
atopic dermatitis (3 papers, 2020 to 2024). "The most common allergens from the family of vicilin, legumin and 2S albumin in the population of children aged 0–5 years with chronic symptoms of atopic dermatitis were peanuts: Ara h 1 (18.4%), Ara h 2 (17.1%), Ara h 6 (15.8%) and Ara h 3 (11.8%)." (PMID 36675318, 2023).
B-cell lymphomas (3 papers, 2020 to 2025). "We explore the role of low serum albumin (≤3.5 g/dL) as an independent risk factor in elderly patients with aggressive B‐cell lymphoma." (PMID 35847697, 2020). "In conclusion, low serum albumin is an independent risk factor in elderly patients with aggressive B‐cell lymphoma treated with R‐CHOP." (PMID 35847697, 2020). "Our study demonstrated that low serum albumin prior to therapy is an independent unfavorable risk factor in elderly patients with aggressive B‐cell lymphoma." (PMID 35847697, 2020). "Serum albumin was significantly lower in both T-cell and B-cell lymphomas than healthy controls (p=0.007)." (PMID 35765478, 2022). "Our study establishes in a large, well‐defined clinical trial population pretreatment serum albumin levels as a cheap and easily available independent prognostic factor for survival in elderly patients with aggressive B‐cell lymphoma in the R‐CHOP era." (PMID 35847697, 2020).
Budd-Chiari syndrome (3 papers, 2021 to 2025). "The patient with Budd–Chiari Syndrome (BCS) was an 8‐year‐old female who presented with high protein (3.2 gm/dL) and high serum ascitic albumin gradient (SAAG) (1.3 gm/dL) ascites for 12 weeks." (PMID 33490609, 2021).
bundle branch block (3 papers, 2021 to 2024). A bundle branch block refers to a defect of the heart's electrical conduction system in which the bundle branch may cease to conduct electrical impulses appropriately. "In Model 3, serum albumin entered the model and a lower albumin was associated with a higher risk of sudden death, but heart rate and bundle branch block on ECG dropped out of the model." (PMID 33301080, 2021).
cellulitis (3 papers, 2021 to 2025). Inflammation of the dermis and subcutaneous tissues caused by a bacterial infection. "The recently developed Baseline Recurrence Risk in Cellulitis score (BRRISC score) individuate patients at risk of recurrent cellulitis based on eight variables (age, heart rate, urea, platelets, albumin, previous cellulitis, venous insufficiency and liver disease)." (PMID 39882704, 2025). "Furthermore, the AUC of albumin (AUC = 0.821), pH (AUC = 0.858) and TP (AUC = 0.878) in the fluid revealed excellent discrimination for differentiating NSTI from cellulitis." (PMID 34998403, 2022).
cerebral malaria (3 papers, 2006 to 2023). A sequestration of Plasmodium falciparum in the brain, which can cause coma and/or seizures. "Moreover, an association between low serum albumin levels and both a longer parasitemia time and a higher incidence of cerebral malaria has been found." (PMID 36979511, 2023). "As heme toxicity contributes to cerebral malaria pathogenesis, a specific neuroprotective effect of albumin can be hypothesized." (PMID 36979511, 2023).
cerebral microbleeds (3 papers, 2024). Cerebral microbleeds are a group of pathological processes affecting the small arteries, arterioles, capillaries and venules of the brain, as detected by brain imaging techniques. "For example, genetic polymorphisms, such as the APOE ε4 allele associated with an increased burden of cerebral microbleeds, as well as those related to lipid metabolism or inflammation could modulate the impact of NHR or the Albumin to Globulin ratio on CMBs risk." (PMID 39734492, 2024).
childhood cancer (3 papers, 2022 to 2024). "Anthropometry and albumin are confounded by fluid status and inflammation, and the Nutrition Screening Tool for Childhood Cancer is the only validated tool in pediatric cancer." (PMID 34998029, 2022).
choledocholithiasis (3 papers, 2023 to 2025). Presence or formation of gallstones in the common bile duct. "The levels of ALT, AST, AFP, T-bil, Ferritin, and HBeAg were significantly elevated, while the levels of Albumin and CHE were markedly reduced in HCC patients compared to choledocholithiasis patients." (PMID 38188679, 2023). "The levels of AFP, Ferritin, and HBeAg were notably increased, while the levels of Albumin and CHE were significantly decreased in HCC patients compared to choledocholithiasis patients." (PMID 38188679, 2023).
chronic lymphocytic leukemia (3 papers, 2012 to 2026). "Human albumin has been shown to protect against apoptosis of chronic lymphocytic leukemia cells and endothelial cells, to decrease reactive oxidant-induced neuronal apoptosis, to promote neuronal survival, and to increase energy metabolism in primary astrocytes." (PMID 22815976, 2012).
coccidiosis (3 papers, 2023 to 2025). A parasitic infection caused by Coccidia. "Biochemically, compared to the infected group, ginger (Zingiber officinale) reversed the altered biochemical parameters (total protein, albumin, MDA, and SOD enzyme) associated with cecal coccidiosis." (PMID 40230796, 2025). "Coccidiosis development in d-CON was associated with impaired productivity (lower DWG and higher DFI and FCR relative to h-CON; p < 0.05) and altered serum biochemistry (decreased TP, ALB, and GLB concentrations and SOD, GST, and GPx activities relative to h-CON; p < 0.05)." (PMID 36903445, 2023). "More specifically, in the coccidiosis-challenged chickens of the d-CON group, TP, ALB, and GLB concentrations were significantly decreased in comparison with the h-CON group (p < 0.05)." (PMID 36903445, 2023).
Constipation (3 papers, 2017 to 2025). Infrequent or difficult evacuation of feces. "These included drugs used to treat nausea (ondansetron, promethazine), constipation (lactulose, senna glycosides, metoclopramide, docusate, silicones), and end‐stage liver disease (albumin, lactulose, sucralfate)." (PMID 41345999, 2025). "Constipation and non-constipation groups were compared for age; sex; body mass index; bed rest period; use of anti-epileptic drugs, valproate sodium, or enteral nutrition; and serum levels of albumin, pre-albumin, totalcholesterol, free carnitine, folic acid, and trace elements." (PMID 28366991, 2017).
cryptococcosis (3 papers, 2020 to 2023). An acute or chronic, localized or disseminated infection by Cryptococcus neoformans. "Decreased serum albumin level was identified as an independent risk factor for disseminated cryptococcosis in the PC group." (PMID 38115055, 2023). "In addition, patients with cryptococcosis had significantly higher alanine aminotransferase, alkaline phosphatase, ferritin, and lactate dehydrogenase, but lower albumin than those without cryptococcus (all p < 0.05)." (PMID 36294675, 2022).
Cryptosporidium infection (3 papers, 2020 to 2024). "First, we performed a target database search to obtain a total of 47 intersecting targets of oxymatrine for the treatment of cryptosporidiosis, including the core targets of ALB, IL-6, TNF, AKT1, CASP3, and SRC." (PMID 38914662, 2024). "Additionally, it was previously reported that the level of γ globulin was markedly reduced while albumin was insignificantly affected in Cryptosporidium infection." (PMID 33076496, 2020). "A previous study reported that albumin was not significantly affected, whereas globulin decreased significantly during Cryptosporidium infection." (PMID 35095858, 2021).
cystitis (3 papers, 2019 to 2026). Inflammation of the urinary bladder. "In CYP-induced mouse cystitis, albumin administration markedly reduced bladder enlargement, edema, and hemorrhage, effectively normalizing the bladder weight." (PMID 42072657, 2026). "Notably, oral albumin supplementation similarly attenuated CYP-induced cystitis." (PMID 42072657, 2026).
Dengue hemorrhagic fever (3 papers, 2016 to 2024). A serious condition caused by Dengue virus infection. "All studies consistently reported that individuals who progressed to dengue haemorrhagic fever had lower serum albumin concentrations than individuals who did not progress to dengue haemorrhagic fever during the febrile phase, with low to moderate heterogeneity and no publication bias." (PMID 33640077, 2021).
disseminated tuberculosis (3 papers, 2014 to 2025). "The median level of ALB in patients with miliary tuberculosis was significantly lower than in those complicated with CNS tuberculosis." (PMID 28531173, 2017). "In the ROC analysis, we found that ALB could be used to differentiate miliary tuberculosis and miliary tuberculosis with CNS tuberculosis for its high AUC of 0.83, with a sensitivity of 71.0% and specificity of 81.6% at the cut-off point of 38.85 g/L." (PMID 28531173, 2017). "Thus, we concluded that ALB is the independent risk predictor, and other factors, including cough, nausea, headache, HGB, ESR and CRP are non-independent predictors for CNS tuberculosis in patients with miliary tuberculosis." (PMID 28531173, 2017). "Factors including age, cough, nausea, headache, HGB, ALB, ESR and CRP have been proved to be significantly different between patients with miliary tuberculosis and miliary tuberculosis patients complicated with CNS tuberculosis." (PMID 28531173, 2017). "Many studies have shown decreased levels of HGB and ALB, elevated levels of adenosine deaminase (ADA) and CRP, and increased ESR in miliary tuberculosis patients." (PMID 28531173, 2017). "In a sensitivity analysis, the hazard ratio for mortality was 1.44 (95% CI, 1.16–1.79, P = 0.001) after adjusting for age, serum albumin, CD4 cell counts, homelessness, illiteracy, belonging to a disadvantaged community, gender, positive sputum smear, disseminated tuberculosis, and previous ATT." (PMID 25013814, 2014).
diverticulitis (3 papers, 2021 to 2023). An infection that develops in the diverticula of the intestinal tract. "This study showed an association between serum UA levels and colonic diverticulosis after adjusting for factors such as age; sex; serum LDL, creatinine, AST, albumin, Na, and HsCRP levels; smoking history; alcohol consumption; and exercise habits." (PMID 35951520, 2022). "In univariate logistic regression analysis, it showed that age, HTN, DM, left-sided diverticulitis, mHG, lymphocytes, WLR, NLR, PLR, CRP levels, CRP/albumin ratio, and mGPS were markedly associated with the non-operative treatment failure for diverticulitis." (PMID 36927780, 2023). "Regarding laboratory values, patients with complicated diverticulitis had higher levels of absolute neutrophils (AUC 0.73), higher white blood cells (AUC 0.70), platelet count (AUC 0.68) and lactate (AUC 0.61), and lower levels of albumin (AUC 0.69), chloride (AUC 0.64), and sodium (AUC 0.61)." (PMID 34829448, 2021). "Patients with complicated diverticulitis had higher absolute neutrophils (NEUT), white blood cells (WBC), platelets count (PLT), and lactate levels, and lower albumin, chloride (Cl), and sodium (Na) levels." (PMID 34829448, 2021).
Dyskinesia (3 papers, 2020 to 2023). A movement disorder which consists of effects including diminished voluntary movements and the presence of involuntary movements. "The duration of the disease, UPDRS-III score, H-Y stage, dyskinesia, MMSE score, HAMA score, HAMD score, NMS score, LEDD, ALB level, P level, TP level, UA level, and ADA level were regarded as independent variables." (PMID 33362679, 2020).
enteritis (3 papers, 2019 to 2021). Inflammation of the small intestine. "Protein losses (requiring human serum albumin treatment) could be due to polyserositis and interstitial losses (due to increased permeability of the serous membranes) or perhaps enteritis losses." (PMID 34576853, 2021).
Erythema (3 papers, 2010 to 2024). Redness of the skin, caused by hyperemia of the capillaries in the lower layers of the skin. "Although initiation of cyclosporine resulted in decrease in the intensity of erythema, the response was more dramatic after 20% salt free albumin was infused with complete resolution of the waves of pustulation during the pregnancy." (PMID 20606891, 2010).
esophageal adenocarcinoma (3 papers, 2020 to 2023). A malignant tumor with glandular differentiation arising predominantly from Barrett mucosa in the lower third of the esophagus. "Nanoparticle albumin bound paclitaxel (NPT) has superior antitumor activity over paclitaxel against esophageal adenocarcinoma." (PMID 34621175, 2021).
Esophageal tumor (3 papers, 2022 to 2025). "Esophageal tumor surgery under OLV had a significant effect on major inflammatory cell types as well as albumin, in particular by increasing the neutrophil count and decreasing the lymphocyte count." (PMID 40007585, 2025). "Reexamination showed that all lesions disappeared after 2 cycles of sintilimab plus albumin-bound paclitaxel, nedaplatin, and palliative radiotherapy for esophageal tumors, and positron emission tomography demonstrated the absence of tumor metabolic activity following treatment." (PMID 36033564, 2022).